SULT1E1 (sulfotransferase family 1E member 1)
Diseases named in the same sentence as SULT1E1 in open-access papers (continued):
Sharing a sentence is not in itself a finding about the gene and the disease.
phaeochromocytoma (2 papers, 2016 to 2024). "However, some genes associated with steroid, organic hydroxy compound, and alcohol-related processes that were upregulated in ZG samples from phaeochromocytoma patients (eg, CYP11B2, CYP39A1, PLA2G1B, and SULT1E1), were not significantly upregulated in ZG samples from adrenals with an APA." (PMID 27777363, 2016).
-dependent (1 paper, 2019). "However, drugs targeting estrogen inactivation enzyme, estrogen sulfotransferase (SULT1E1), have not been developed for estrogen-dependent cancer treatment or prevention." (PMID 36312461, 2019).
atherosclerosis (1 paper, 2022). A disease characterized by the build-up of fatty material and calcium deposition in the arterial wall resulting in partial or complete occlusion of the arterial lumen. "Decreased circulating estrogen levels, along with estrogen sulfotransferase (SULT1E1), in diabetic postmenopausal women may contribute to an increased risk of atherosclerosis development." (PMID 36142876, 2022).
cervical cancer (1 paper, 2023). A primary or metastatic malignant neoplasm involving the cervix. "The results showed that high expression of MYH1, MYH4, FGG, and DEPP1 was associated with shorter overall survival of patients with cervical cancer; high expression of SULT1E1, RAB3C, CXCR3, and PROX2 was associated with longer overall survival of patients with cervical cancer." (PMID 37350944, 2023). "High expression of MYH1, MYH4, FGG, DEPP1, and ZBTB16 was associated with shorter overall survival of patients with cervical cancer; high expression of SULT1E1, RAB3C, CXCR3, and PROX2 was associated with longer overall survival of patients with cervical cancer." (PMID 37350944, 2023). "Further studies may be required to elucidate the interaction between HPV16 oncoproteins and SULT1E1 in cervical cancer." (PMID 37350944, 2023).
cholestasis (1 paper, 2022). Impairment of the bile flow caused by obstruction within the liver, or outside the liver in the bile duct system. "For the suppression of SULT1E1, it was also reported that cholestasis-induced farnesoid X receptor activation can lead to a reduction in SULT1E1 in cirrhotic liver tissues and, therefore, impede hepatic deactivation of estrogens in PBC." (PMID 35326489, 2022).
colon cancer (1 paper, 2021). "STS and SULT1E1 expression were detected in 60% and 40%, respectively, of the colon cancer samples examined, but only SULT1E1 expression was detected in non-neoplastic colonic tissues." (PMID 34064842, 2021).
inflammatory bowel disease (1 paper, 2022). A spectrum of small and large bowel inflammatory diseases of unknown etiology. "Some genes, for example SULT1B1 (OMIM 608436) and SULT1E1 (OMIM 600043), have been associated with HS and inflammatory bowel disease." (PMID 35203664, 2022).
Insulin resistance (1 paper, 2013). Increased resistance towards insulin, that is, diminished effectiveness of insulin in reducing blood glucose levels. "In SULT1E1 knock-out mice, loss of SULT1E1 causing an excess of estrogens leads to the formation of smaller patches from white fat and insulin resistance." (PMID 23476785, 2013).
ischemic stroke (1 paper, 2012). A stroke disorder caused by obstruction of blood flow to the brain, due to thrombotic (local blood clot formation) or embolic (due to a blood clot or other material traveling from another site) event. "Odds ratio and 95% confidence interval for the risk of ischemic stroke associated with individual SULT1E1 and COMT and estradiol level." (PMID 23112845, 2012). "To determine the ischemic stroke risk contribution of SULT1E1, COMT and ESR1, we examined whether the genotypic and allelic distribution of the gene differed between the 305 cases and 309 controls (301 cases and 308 controls had results of complete 4 SNPs)." (PMID 23112845, 2012). "We further found that lower estradiol level could increase the risk of young ischemic stroke for those who carry either SULT1E1 or COMT risk genotypes, showing a significant interaction effect (P for interaction = 0.0174)." (PMID 23112845, 2012). "Among participants with Val/Val genotype, SULT1E1 -64G/A is the strongest risk factor, and the combination of COMT Val/Val genotype and SULT1E1 A/A genotype exhibited the highest risk of ischemic stroke with 73.5% patients rate (OR, 6.57; 95%CI, 2.55–16.94; p<0.0001)." (PMID 23112845, 2012). "Moreover, lower estradiol level could increase risk of young ischemic stroke for those who carried either COMT or SULT1E1 risk genotypes." (PMID 23112845, 2012). "Genotype and allelic frequencies of the SULT1E1, COMT, and ESR1 genes in ischemic stroke patients and controls and the estimated odds ratio and 95% confidence interval of ischemic stroke risk." (PMID 23112845, 2012). "Using different analytic strategy, however, MDR and CART method showed consistent result that there was a strong gene-gene interaction between SULT1E1 -64G/A and COMT Val158Met on the risk of young ischemic stroke." (PMID 23112845, 2012). "However, there are no studies exploring the hormone metabolism and signaling pathway genes together on ischemic stroke, including sulfotransferase family 1E (SULT1E1), catechol-O-methyl-transferase (COMT), and estrogen receptor α (ESR1)." (PMID 23112845, 2012). "SULT1E1 -64G/A, COMT Val158Met, ESR1 c.454−397 T/C and c.454−351 A/G genes were genotyped and compared between cases and controls to identify single nucleotide polymorphisms associated with ischemic stroke susceptibility." (PMID 23112845, 2012). "The present study was carried out with the aim to determine whether SULT1E1 -64G/A, COMT Val158Met, ESR1 c.454−397 T/C and c.454−351 A/G genes are associated with ischemic stroke of the young and to further explore the gene-gene and gene-environment interactions for young ischemic stroke patients." (PMID 23112845, 2012). "Traditional multiple logistic regression results also showed that there was a significant interaction effect between SULT1E1 -64G/A and COMT Val158Met for development of young ischemic stroke." (PMID 23112845, 2012). "The logistic regression model also showed there was a significant interaction effect between SULT1E1 -64G/A and COMT Val158Met on ischemic stroke of the young (P for interaction = 0.0171)." (PMID 23112845, 2012).
liver fibrosis (1 paper, 2021). "The molecules, including Scd1, Acta2, collagen type I alpha 1 chain (Col1a1), Timp1, Foxm1, Sult1e1, and plasminogen activator (Plat), are also involved in hepatotoxicity pathways, such as liver fibrosis, liver hyperplasia/hyperproliferation, liver proliferation, and liver necrosis/cell death." (PMID 34539442, 2021).
lung carcinoma (1 paper, 2020). "Overexpression of BAG2 has been associated with poor disease‐specific survival in lung cancer, whereas the SULT1E1 polymorphism rs4149525 has been associated with shortened overall survival in NSCLC." (PMID 34766125, 2020).
meningioma (1 paper, 2023). A generally slow growing tumor attached to the dura mater. "To validate our finding of the association between MC SULT1E1+ subpopulation and high‐grade meningiomas, we examined the signature‐gene expression of this subpopulation using the Gene Expression Omnibus (GEO) dataset." (PMID 36994665, 2023). "SRT1720 is a potential agent for systemic treatment and radiation sensitization for high‐grade meningiomas by inhibiting SULT1E1+ cell subpopulation." (PMID 36994665, 2023). "In this study, scRNA‐Seq is used to identify a unique initiating cell subpopulation (SULT1E1+) in high‐grade meningiomas." (PMID 36994665, 2023). "Following transplantation, the MOs containing the MC SULT1E1+ subpopulation had the capacity for brain invasion, a unique biological behavior identical to that of high‐grade meningiomas." (PMID 36994665, 2023). "We validated the clinical significance of the MC SULT1E1+ subpopulation in high‐grade meningiomas by using both GEO datasets and immunostaining of FFPE tissues." (PMID 36994665, 2023). "We next treated similar‐sized SULT1E1+ MOs with these three compounds at concentrations that had shown significant inhibition of the primary meningioma cell lines (PMCs)." (PMID 36994665, 2023). "A comprehensive analysis suggests that this subpopulation, SULT1E1+, plays an important role in the genesis and recurrence of high‐grade meningiomas." (PMID 36994665, 2023). "Immunostaining with anti‐synapsin‐1, anti‐neurofilament, and anti‐SSTR2a antibodies clearly showed destruction of brain cortex and residual cortex tissue surrounded by meningioma tumor cells, further proving the brain invasion of SULT1E1+ MOs." (PMID 36994665, 2023). "Because our data suggested that the MC SULT1E1+ subpopulation might play a key role in the malignancy of high‐grade meningiomas, we next investigated potential therapeutic strategies by inhibiting this unique subpopulation." (PMID 36994665, 2023). "In summary, we identified a tumor cell subpopulation, MC SULT1E1+, which was exclusive to the grade II meningioma sample and might plays an important role in the tumor progression." (PMID 36994665, 2023). "SULT1E1+ cell subpopulation may directly modulate the behavior of other tumor cells and trigger the M2‐like polarization of macrophages in high‐grade meningiomas." (PMID 36994665, 2023). "Combining these results, we speculated that the MC SULT1E1+ subpopulation directly mediates oncogenesis and development of high‐grade meningiomas." (PMID 36994665, 2023). "We noticed that a minority of grade I meningioma samples also contained a few SULT1E1+ cells." (PMID 36994665, 2023). "Notably, the MC SULT1E1+ subpopulation was found only in the grade II meningioma sample, which was confirmed by quantifying the proportions of the different subpopulations in the meningioma." (PMID 36994665, 2023). "Immunohistochemical staining of FFPE tissues showed a significantly increased number of MC SULT1E1+ cells in grade II/III and recurrent meningioma samples compared with grade I and primary meningioma samples." (PMID 36994665, 2023). "By targeting the SULT1E1+ subpopulation, we identified SRT1720, an SIRT1 agonist, as a potential systemic treatment and radiation sensitizer for high‐grade meningiomas." (PMID 36994665, 2023). "Many signature genes in this subpopulation, including SULT1E1, EDNRA, and EPHA7, were highly expressed in grade II/III meningioma samples." (PMID 36994665, 2023). "MOs derived from meningiomas with or without the MC SULT1E1+ subpopulation were transplanted." (PMID 36994665, 2023).
nonalcoholic steatohepatitis (1 paper, 2021). "Chunhua Wang and colleagues showed that Sult1e1 was downregulated in NAFLD, and another study revealed that Sult1e1 was upregulated in nonalcoholic steatohepatitis." (PMID 33691721, 2021).
Ovarian tumors (1 paper, 2021). "Ovarian tumors express conjugation phase enzymes as well; moreover, the GST class-pi (GSTP1) enzyme has been reported as one of the most abundantly expressed genes in ovarian tumors, whereas the sulfotransferase SULT1E1 as an independent positive prognostic factor in HGSOC." (PMID 34638494, 2021).
Sepsis (1 paper, 2020). Sepsis is defined as life-threatening organ dysfunction caused by a dysregulated host response to infection. "Ablation of the Sult1e1 gene increased susceptibility to LPS-induced sepsis in mice." (PMID 32193417, 2020).
thrombosis (1 paper, 2022). "SULT1E1 is also reportedly linked to foetal development, and ablation of the murine SULT1E1 gene causes placental thrombosis and spontaneous foetal loss." (PMID 35581549, 2022).
type 1 diabetic (1 paper, 2020). "Hepatic SULT1E1 mRNA levels are constitutively up-regulated in type 1 diabetic Akita mice; CAR spontaneously accumulates in the nucleus and activates the Sult1e1 promoter by recruiting phosphorylated ERα in the liver as observed with PB-induced livers." (PMID 32193417, 2020).
cancer (22 papers, 2011 to 2025). A tumor composed of atypical neoplastic, often pleomorphic cells that invade other tissues. "Oxidant-stress neutralizer, chalcone (trans-1,3-diaryl-2-propen-1-ones) and SULT1E1-inducer pure dialyl-sulfide (garlic; Allium sativum) were tested to prevent cancer causing factors in rat, in-vitro and in-vivo." (PMID 39132498, 2024). "Estrogens must be inactivated after their actions in vivo by SULT1E1, uncontrolled estrogen activity in certain tissues will cause cancers." (PMID 36312461, 2019). "SULT1E1 was related to the metabolism of estrogen, so phthalate monoesters may cause certain cancer by disturbing the metabolism of estrogen." (PMID 35528018, 2022). "In this cancer, it is an adaptive strategy by increasing SULT1E1 gene and protein expression, tissues make an initial attempt to get rid of extra amount of E2." (PMID 39132498, 2024). "Anti-estrogens and other cancer therapeutic drugs have been shown to alter SULT1E1 protein/gene expressions and E2 signalling rate." (PMID 32158360, 2020). "SULT1E1 is a protective factor in both BRCA and PAAD, however, The other two markers play opposite roles in the two types of cancer (risk factor and protective factor)." (PMID 31888612, 2019). "The expression of SULT1E1 was significantly downregulated (p = 0.0392) in cancer tissue from premenopausal women, with significantly lower levels seen in cancer and adjacent control tissue from postmenopausal women as compared to premenopausal women." (PMID 28690541, 2017). "High expression of STS and low expression of SULT1E1 will increase levels of active estrogens in malignant tumor cells leading to the stimulation of cell proliferation and cancer progression." (PMID 23476785, 2013). "For the first time, we are revealing that advanced cancer tissue with elevated SULT1E1-protein may reactivate in a reducing-state initiated by chalcone, but remain dormant in an oxidative environment." (PMID 39132498, 2024). "The expression of SULT1E1 in the tumor microenvironment may also become unfavourable for the cancer cells as it will restrict the estrogen dependent activation of Nrf2." (PMID 31114446, 2019). "Also SULT1E1 was detected in epithelial ovarian cancer with significantly higher immunohistochemical levels seen in low grade cancers versus high grade cancers." (PMID 37188267, 2023). "Thus, where CAR and SULT1E1 genes are co-expressing, garlic may affect cancer formation and development by affecting SULT1E1 gene expression." (PMID 21698271, 2011). "Regarding the link between cancer and ABA, it is worthwhile to single out the sulfotransferase 1E1 (SULT1E1)." (PMID 41303597, 2025). "Thus, induction and activation of SULT1E1 might become cancer prevention and treatment strategy." (PMID 39132498, 2024). "Accordingly, if once estrogen has induced cancer; functional inability of ER would not be able to compensate the availability of E2 favored by low SULT1E1 and high sulfatase under oxidative stress." (PMID 31114446, 2019). "However, estrogen inactivation enzyme SULT1E1 has not been targeted to develop estrogen-dependent cancer drugs." (PMID 36312461, 2019).
tumor (21 papers, 2009 to 2026). "The distribution and localization of SULT1E1 was noticed in stromal tissue, adipose lining and nucleus in both tumor and corresponding surrounding tissues." (PMID 39132498, 2024). "Our findings abide by earlier study that suggests that SULT1E1 is expressed more in the tumor tissues as compared to their surroundings, and our study is the first attempt to explain that, though SULT1E1 is overexpressed in tumor it remains inactive." (PMID 39132498, 2024). "The expression of HIF1α in tumor tissue was remarkably higher when compared to their corresponding surrounding tissues which was noticed in SULT1E1 expression." (PMID 39132498, 2024). "An enhanced level of SULT1E1 has been found in tumor tissues in earlier research as part of an adaptation mechanism to control active E2." (PMID 39132498, 2024). "Densitometric data is displayed along with the SULT1E1 (gene) expression RTPCR data in tumor (n = 5) and adjacent (n = 3) tissue." (PMID 39132498, 2024). "It is shown that dexamethasone (DEX) treatment increased hepatic and MCF-7/VEGF tumor expression of Sult1e1/SULT1E1." (PMID 39132498, 2024). "Expression of SULT1E1 protein in tumor was comparatively higher than corresponding surrounding tissues." (PMID 39132498, 2024). "A few surrounding tissues have shown an increased SULT1E1 expression, whose corresponding tumor shows more intense SULT1E1 expression." (PMID 39132498, 2024). "Tumor tissue was darkly stained for SULT1E1 compared to the surrounding suggesting increased expression." (PMID 39132498, 2024). "Densitometric data are displayed along with the calculation of SULT1E1 (protein) expression in tumor (n = 6) tissue and the comparable surrounding (n = 6) tissue." (PMID 39132498, 2024). "Most importantly, the MOs retained the SULT1E1+ subpopulation from the corresponding parental tumor." (PMID 36994665, 2023). "Meanwhile, some MOs didn't contain SULT1E1+ subpopulation cells and consisted with other tumor cell subpopulations." (PMID 36994665, 2023). "When all the disease groups are compared together it is noticed that SULT1E1 expressions in the tumor tissues are highly correlated to that of the surrounding tissues." (PMID 32158360, 2020). "SULT1E1 expression and E2-level were increased in tumor-tissue compared to their corresponding surrounding-tissues." (PMID 32158360, 2020). "Breast tissue SULT1E1 expressions in both grades-II and grade-IV disease conditions were noticed to be significantly correlated with tumor expressions of Nrf-2." (PMID 32158360, 2020). "In case of tumor tissues SULT1E1 is positively correlated with NPSH (p < 0.023) and MDA (p < 0.042)." (PMID 32158360, 2020). "An irregular pattern of SULT1E1 expression was noticed, in some of the cases including IIIB, IIIA, SULT1E1 was found to be highly expressed in the tumor tissue compared to their corresponding surrounding tissues." (PMID 32158360, 2020). "Oxidative-stress induces SULT1E1 via Nrf2/NFκβ cooperatively in tumor-pathogenesis to maintain the required proliferative-state under enriched E2-environment." (PMID 32158360, 2020). "Our earlier study showed that E2 administration to human tumor xenografted rat impaired SULT1E1 protein/mRNA expression resulting higher plasma E2 level." (PMID 32158360, 2020). "NFκβ expressions were found to be significantly correlated with Nrf-2 and SULT1E1 expressions in the tumor tissues." (PMID 32158360, 2020). "Similar to the disease grade II, surrounding NPSH was found to be positively correlated to the tumor SULT1E1 (p < 0.049)." (PMID 32158360, 2020). "The strength of SULT1E1 staining in tumor is stronger than corresponding surrounding tissue." (PMID 39132498, 2024). "These proteins and SULT1E1-mRNA expressions were significantly higher in tumor (p < 0.05)." (PMID 39132498, 2024). "The strong interactions between MC SULT1E1+ and macrophages and monocytes suggest that this unique subpopulation might be involved in M2‐like polarization and tumor development." (PMID 36994665, 2023).